BCL3 (BCL3 transcription coactivator)
Diseases named in the same sentence as BCL3 in open-access papers (continued):
Sharing a sentence is not in itself a finding about the gene and the disease.
lymphoma (13 papers, 2010 to 2024). A malignant (clonal) proliferation of B- lymphocytes or T- lymphocytes which involves the lymph nodes, bone marrow and/or extranodal sites. "The product BCL3 transcription coactivator (BCL3) is known to be associated with B cell leukemia/lymphoma and it is a member of the IkB (inhibitors of kB proteins) family." (PMID 33333988, 2020). "The inhibition of LPS-induced TNF-α expression in macrophages has been shown to be mediated by IL-10, the expression of which is promoted by BCL3 (B-Cell Leukemia/Lymphoma)." (PMID 32759853, 2020). "Bcl3 is involved in some cancers, the most known is his role in lymphoma, in which he regulates pro-survival and pro-inflammatory gene expression." (PMID 32659965, 2020). "While Bcl-3 overexpression was originally found to be associated with CLL and lymphomas, recent reports have shown that this oncogene is overexpressed in several solid tumors, such as breast, nasopharyngeal and endometrial carcinomas." (PMID 20731879, 2010). "As important regulators of cell proliferation and survival, BCL3 and IκBζ might emerge as attractive therapeutic targets to dampen excessive NF-κB activity in certain lymphoid cancers, possibly by pharmacologically preventing the interaction between p50 and BCL3 or IκBζ." (PMID 29587428, 2018). "Differentially regulated genes were enriched for classical lymphoma driver genes downstream of the BCR, including MALT1 and CARD11, as well as NFATC2, TNFRSF13C (BAFF), and components of the NF-κB (RELB, IRAK1, BCL3, and TNFRSF1B) pathway." (PMID 39082968, 2024). "The ‘DH’ lymphomas are defined as a chromosomal breakpoint affecting the MYC/8q24 and another recurrent genetic abnormality, mainly involving BCL2, BCL6, BCL3 or other genes." (PMID 32459397, 2020). "The distinctive mBL signature consisted of 58 genes, including several target genes of the NF-κB pathway (i.e., BCL2A1, FLIP, CD44, NFKBIA, BCL3, and STAT3) that are known to distinguish activated B-cell-like or germinal center B-cell-like lymphomas." (PMID 26416427, 2015).
colitis (11 papers, 2015 to 2025). Inflammation of the colon. "In contrast, global Bcl3‐knockout mice are less susceptible than wild‐type mice to DSS‐induced colitis." (PMID 40359334, 2025). "In contrast, Rag1–/– mice that received Bcl‐3‐deficient T cells were protected from transfer‐induced colitis." (PMID 40359334, 2025). "They noted that the overexpression of T cell-specific Bcl-3 causes a decrease in NF-κB activity, which gives rise to abnormal development and function of Tregs, causing spontaneous colitis." (PMID 35355979, 2022). "In T cell-dependent autoimmune diseases, studies have found that deletion of Bcl-3 in T cells blocks colitis and experimental autoimmune encephalomyelitis caused by T cell metastasis." (PMID 35355979, 2022). "An increase in the Bcl-3 expression level will lead to a decrease in NF-κB activity, which will lead to abnormal Treg development and function and cause spontaneous colitis." (PMID 35355979, 2022). "Bcl-3-depleted T cells cannot induce transfer-induced colitis and experimental autoimmune encephalomyelitis (EAE), caused by the decrease of GM-CSF in Th1 and an increase in Th17 cells." (PMID 36159779, 2022). "By contrast, using conditional knockout mice, it was further demonstrated that loss of Bcl-3 specifically in Treg cells was sufficient to boost RORγt+ Treg cell formation and resistance of mice to dextran sulfate sodium-induced colitis." (PMID 35672519, 2022). "Here the authors show that Bcl-3 impedes NF-κB DNA binding to alter T regulatory cell development and function, causing spontaneous colitis in mice." (PMID 28452361, 2017). "Work using the dextran-sodium sulfate (DSS) mouse model of colitis showed that colitis was associated with a significant increase in Bcl3 expression, and that Bcl-3-deficiency provided partial protection against disease development." (PMID 27023613, 2016). "Mice with a T‐cell‐specific overexpression of Bcl‐3 develop more severe colitis that can be attributed to defective Treg cell development and function." (PMID 40359334, 2025). "Additionally, Bcl‐3‐deficient T cells may preferentially differentiate toward RORγt+ Treg cells, with increased frequencies of both thymic and microbiome‐induced RORγt+ Treg cells potentially contributing to protection against colitis." (PMID 40359334, 2025). "Mice with T-cell-specific overexpression of Bcl-3 induced defective development and function of Tregs, aggravating colitis." (PMID 36159779, 2022). "Not coincidentally, in T-cell-dependent autoimmune diseases, deletion of T-cell-specific Bcl-3 exacerbated part of the lupus-like phenotype but blocked T-cell transfer resulting in colitis and experimental autoimmune encephalomyelitis." (PMID 35355979, 2022). "The latest study defines the relevant mechanism by which an increase in Bcl-3 levels restricts the development and function of Treg cells, leading to spontaneous colitis." (PMID 35355979, 2022). "Our prior work demonstrated critical cell-autonomous contributions of Bcl-3 in maintaining pathogenic Th1-like, IFN-γ producing CD4+ T cells in the context of EAE and colitis." (PMID 33508001, 2021). "This links to other data showing Bcl-3 KO cells in mice colons displayed increased caspase-3 cleavage following dextran-sodium sulphate-induced colitis, suggesting these cells were undergoing more apoptosis." (PMID 31930327, 2020). "Effects of BCL-3 KO have been studied in a variety of different inflammatory models, including pancreatitis, colitis, dermatitis and rheumatoid arthritis." (PMID 31930327, 2020). "Mice with T-cell-specific overexpression of Bcl-3 develop severe colitis that can be attributed to defective Treg cell development and function, leading to the infiltration of immune cells such as pro-inflammatory γδT cells, but not αβ T cells." (PMID 28452361, 2017). "In this study, we demonstrate that Bcl-3 is important for the maintenance of Treg cell function and the prevention of spontaneous colitis." (PMID 28452361, 2017).
colitis (continued). "Quantification of this analysis revealed a significant increased cell infiltration of all tested immune cells in the colon of Bcl-3-overexpressing mice, confirming the increased score of colitis as measured by mini-endoscopy." (PMID 28452361, 2017). "This treatment also resulted in elevated intestinal epithelial cell proliferation in Bcl-3 knockout mice compared with the control, suggesting that Bcl-3 plays a major role in regulating proliferation and sensitivity to chemically induced colitis." (PMID 25929479, 2015). "In mice, deletion of Bcl-3 protected against chemically-induced colitis compared to wild-type animals." (PMID 25929479, 2015). "Importantly, CD4+ T cells overexpressing Bcl‐3 fail to induce colitis in a T cell transfer‐induced colitis experiment, presumably due to impaired proliferation of these cells in vivo, which is a prerequisite for inducing colitis in this model." (PMID 40359334, 2025). "This study thus reveals intrinsic functions of Bcl-3 in Treg cells, identifies Bcl-3 as a potential prognostic marker for colitis and illustrates the mechanism by which Bcl-3 regulates NF-κB activity in Tregs to prevent colitis." (PMID 28452361, 2017). "In mice, we could define a clear role for Bcl-3 in intestinal inflammation, as mice overexpressing Bcl-3 in T cells develop spontaneous colitis." (PMID 28452361, 2017). "Consistently, Bcl3 was reported to maintain a pathogenic Th1 cell phenotype and prevent conversion to a Th17-like cell with a nonpathogenic phenotype in T cell transfer-induced colitis." (PMID 35351855, 2022). "According to these findings, Bcl-3-depleted T cells could not cause T cell transfer-induced colitis or EAE." (PMID 36159779, 2022). "Recipients of wild-type T cells succumb to colitis 6–7 weeks after transfer due to the development of IFN-γ+ TH1 cells, but remarkably, when T cells from Bcl3−/− mice were used the recipients remained healthy." (PMID 27023613, 2016). "This analysis revealed an impaired proliferative capacity of Bcl-3-overexpressing CD4+ T cells compared with control CD4+ T cells upon stimulation, an impairment that can explain the failure of these cells to induce transferred colitis." (PMID 28452361, 2017). "Surprisingly, mice overexpressing Bcl-3 specifically in Treg cells (Bcl-3FoxP3OE mice) did not develop any signs of colitis probably due to the very high percentage of GFP− Foxp3+ Treg cells, which was less pronounced using CD4-Cre." (PMID 28452361, 2017). "Bcl-3 is an atypical NF-κB family member that regulates NF-κB-dependent gene expression in effector T cells, but a cell-intrinsic function in regulatory T (Treg) cells and colitis is not clear." (PMID 28452361, 2017). "In line with this, mice that overexpress Bcl-3 in T cells develop severe spontaneous colitis, which is not mediated by effector T cells but instead is caused by impaired Treg cell function resulting from altered NF-κB activity via cell-intrinsic regulation by Bcl-3." (PMID 28452361, 2017). "Whether or not the reduced IL-10 production by Bcl-3-overexpressing Tregs is the sole reason for the colitis is not clear, as we also noticed decreased expression levels of Foxp3, CTLA-4, GITR and IL-2R in these Treg cells." (PMID 28452361, 2017). "As T-cell-specific Bcl-3 overexpression drives the development of a strong colonic inflammation similar to the histopathology observed in patients with IBD, we further characterized the colitis phenotype in these mice and examined gene expression of different pro-inflammatory cytokines." (PMID 28452361, 2017). "Interestingly, Bcl-3−/− T cells failed to induce colitis when transferred into Rag1−/− mice, suggesting an inability of Bcl-3−/− T cells to respond to the microbiota-derived and antigen-specific signals that drive colitis in this model." (PMID 31930327, 2020).
B-cell lymphomas (10 papers, 2009 to 2024). "The common deleted genes included BCL3, which is known to be mutated in B cell lymphomas." (PMID 20428235, 2010). "Initially, we investigated the expression levels of Bcl-3 in a panel of B-cell leukemia and B-cell lymphoma cell lines." (PMID 39327470, 2024). "This is consistent with findings of previously studies reporting dysregulation of BCL3 expression in T/B cell leukemia, Hodgkin lymphoma, T/B cell lymphoma." (PMID 30357752, 2019). "This proportion of Bcl-3+ plasma cell malignancies is similar to the proportion of B-cell lymphomas expressing Bcl-3 (6%)." (PMID 19191868, 2009). "Bcl-3 was highly expressed in B-cell lymphoma cell lines: Granta-519, RL, Rec-1, and WSU-NHL, but comparatively low expressed in B-cell lymphoma cell lines: Karpas-422 and SU-DHL-8." (PMID 39327470, 2024). "Patients with B cell lymphomas bearing MYC translocation combined with translocation involving other genes, such as BCL2, BCL3, or BCL6, defined as double-hit lymphoma (DHL), have a poor prognosis." (PMID 28595585, 2017). "The term ‘DH lymphoma’ was initially used to describe mature-B-cell lymphomas with a chromosomal breakpoint affecting the MYC locus in combination with another recurrent breakpoint, such as BCL2, BCL6, BCL3 or CCND1." (PMID 26517511, 2015). "Upon Bcl-3 protein expression analysis in a larger panel of B-cell lymphoma cell lines, we could confirm that B-cell leukemia cell lines RS4;11 and SUP-B15 express lower levels of Bcl-3 compared to most B-cell lymphoma cell lines." (PMID 39327470, 2024).
cervical carcinoma (10 papers, 2013 to 2024). A carcinoma arising from either the exocervical squamous epithelium or the endocervical glandular epithelium. "Other loci were found altered such as Aldehyde dehydrogenase 2 (ALDH2) and isocitrate dehydrogenase 2 (IDH2), that was found to predispose to cervical carcinoma and glioma respectively as well as BCL3, AKT2 and ERCC2 for which polymorphisms were shown to be associated with lung carninoma." (PMID 31105870, 2019). "While addressing KIAA1199 and BCL-3 expressions in cervical cancer cells, we noticed that BCL-3 protein levels were higher in HPV-positive EIL8 and CaSki cells than in the HPV-negative A431 cell line." (PMID 25366117, 2014). "We demonstrated here that KIAA1199 is induced by BCL-3 in immortalized keratinocytes as well as in cervical cancer-derived cells." (PMID 25366117, 2014). "Consistently, KIAA1199 expression relies on BCL-3 in cervical cancer-derived cells as small interfering RNA (siRNA)-mediated BCL-3 depletion impaired KIAA1199 expression in CaSki cells." (PMID 25366117, 2014). "From the genes differentially expressed between early and advanced stages of cervical cancer, six genes – three upregulated (BCL3, IGF2, and PIK3R1) and three downregulated (PTPN4, PERP, and DUSP1) were selected for validation by qRT-PCR." (PMID 24403257, 2013). "Interestingly, endogenous BCL-3 was also recruited on the same κB sites of KIAA1199 promoter in cervical cancer-derived CaSki cells." (PMID 25366117, 2014). "Study have showed that BCL3 was high expression in esophageal squamous cell carcinoma and exerted an oncogenic function by regulating STAT3 in human cervical cancer." (PMID 38767825, 2024). "Although Gal-7 affects the specific cervical cancer networks in different ways, we identified a group of eight molecules that are regulated in both cell lines: CRYAB, TACSTD2, BCL-3, COX19, OASL, CDKN2A/p14ARF, NIBAN/FAM129A, and FST." (PMID 27558259, 2016). "B-cell CLL/lymphoma 3 (Bcl3) may induce cell proliferation and inhibit cell death as an oncogenic gene by regulating STAT3 in several cancers including cervical cancer, glimo cell." (PMID 29545936, 2018). "Thus, BCL-3 is required for EGF-dependent EMT and for cell invasion of cervical cancer cells, at least by promoting KIAA1199 expression." (PMID 25366117, 2014). "Thus, HPV16 positively regulates BCL-3 and KIAA1199 levels in cervical cancer-derived cells." (PMID 25366117, 2014).
glioma (10 papers, 2015 to 2024). A benign or malignant brain and spinal cord tumor that arises from glial cells (astrocytes, oligodendrocytes, ependymal cells). "In contrast, the mechanism of action of BCL3 in controlling apoptosis in glioma cells was defined as a STAT3 mediated regulation of BCL2 and Mcl1 while suppression of BCL3 reduced xenograft tumour growth." (PMID 38195591, 2024). "High BCL-3 expression can promote resistance to alkylating chemotherapy in gliomas." (PMID 37736616, 2023). "BCL3 was reported to be an informative indicator of glioma response to alkylating chemotherapy." (PMID 33147797, 2020).
colon cancer (9 papers, 2015 to 2025). "Compared to adjacent normal colon, upregulation of Defa6 and Bcl3 and downregulation of App, Myh11, and Myl9 indicated changes in tight junctions and anti-microbial activity in Pirc colon tumors." (PMID 34494932, 2021). "This suggests that preventing nuclear localization of Bcl-3 in colon cancer cells facilitates proliferation of these cells." (PMID 25929479, 2015). "To further evaluate the expression level of Bcl-3 in colon cancer, we prepared total cell lysate from SW-48, HT-29, SW-480, CACO-2, HCT-116 and LOVO and found variation in Bcl-3 expression in these cell lines." (PMID 25929479, 2015). "We found that Bcl-3 was mainly localized in the cytoplasm in the tumour tissue isolated from colon cancer patients." (PMID 25929479, 2015). "Future studies are needed to identify the mechanism and signaling pathway that hold Bcl-3 in the cytoplasm of colon cancer cells." (PMID 25929479, 2015). "Surprisingly, we found an accumulation of Bcl-3 in the cytoplasm of colon cancer tissue freshly isolated from three patients." (PMID 25929479, 2015). "To investigate Bcl-3 localization in colon cancer cell lines, we performed biochemical cell fractionation and immunofluorescence staining." (PMID 25929479, 2015). "In the present study, we investigated whether nuclear localization of Bcl-3 in colon cancer has any prognostic value." (PMID 25929479, 2015). "Furthermore, dose-dependent inhibition of COX-2 using NS398 inhibited the expression of Bcl-3 and cyclin D1 in a human colon cancer cell line." (PMID 25929479, 2015). "In addition, we found cytoplasmic localization of Bcl-3 in three human colon cancer cell lines, confirming the results obtained from our freshly isolated tissues and TMA analysis." (PMID 25929479, 2015). "A shift from positive Bcl-3 staining in the nucleus to the cytoplasm could indicate the transition of normal colonic epithelia cells into colon cancer." (PMID 25929479, 2015). "To investigate whether we can observe similar translocation of Bcl-3, colon cancer cell line were stimulated with TPA for 30 minutes." (PMID 25929479, 2015). "In three out of six colon cancer cell lines, we detected elevated levels of Bcl-3." (PMID 25929479, 2015). "However it is not known whether localization of Bcl-3 in colon cancer is similar to other reported studies, and whether localization of Bcl-3 has any prognostic value in colon cancer." (PMID 25929479, 2015).
prostate carcinoma (7 papers, 2015 to 2024). A carcinoma that arises from epithelial cells of the prostate gland. "In prostate cancer, inhibitor of DNA-binding (Id) proteins 1 and 2 were reduced upon Bcl-3 knock-down, leading to a sensitization of chemotherapeutic drug-induced apoptosis." (PMID 39327470, 2024). "In both breast and prostate cancer, the current evidence points to BCL3 having more pronounced effects on cell survival mechanisms and promoting tumour progression (see metastasis section below) than cell cycle regulation." (PMID 38195591, 2024). "In prostate cancer the over-expression of B-cell leukemia 3 (Bcl3) protein is correlated with the expression of Id1 and Id2, which is in turn accompanied with resistance to pro-apoptotic drugs." (PMID 28122577, 2017). "In prostate cancer Bcl3 is overexpressed via IL6, leading to the up-regulation of Id1 and Id2, and inducing resistance against anticancer drugs." (PMID 28122577, 2017). "The proto-oncogene Bcl-3 is known to be overexpressed and localized in the nuclei of different solid tumours such as breast, nasopharyngeal, endometrial and prostate cancer." (PMID 25929479, 2015). "Since STAT3 can regulate Bcl-3 expression in prostate cancer, we wondered whether STAT3 and Bcl-3 expression are also linked in MCF-7 cells." (PMID 26515727, 2015). "Similarly, enforced suppression of BCL3 by shRNA in DU145 prostate cancer xenografts resulted in a significant reduction in tumour growth which correlated with an increase in the number of cleaved caspase-3 positive cells within the treated tumours but no change in mitotic index." (PMID 38195591, 2024). "Notably, Bcl-3 is also important for prostate cancer cell survival during chemotherapy." (PMID 30158439, 2018). "IL-6, in turn, can induce expression of the anti-apoptotic Bcl-3 protein via STAT3 signaling, which can contribute to prostate cancer cell survival." (PMID 30158439, 2018).